RNU6-952P (RNA, U6 small nuclear 952, pseudogene)
Gene: Small nuclear RNA gene on chromosome 11 (102,313,722 to 102,313,829, forward strand). Ensembl gene ENSG00000212466.
Homologues: Orthologues: chimpanzee U6 (97% identical), macaque U6 (91% identical), guinea pig U6 (63% identical). Paralogues in human: RNU6-1145P (74% identical), RNU6-16P (74% identical), RNU6-428P (74% identical), RNU6-1084P (73% identical), RNU6-1316P (73% identical), RNU6-38P (73% identical), RNU6-1031P (72% identical), RNU6-1214P (72% identical), RNU6-1260P (72% identical), RNU6-144P (72% identical), RNU6-20P (72% identical), RNU6-333P (72% identical), and 1286 more.